ABL1 (ABL proto-oncogene 1, non-receptor tyrosine kinase)
Diseases named in the same sentence as ABL1 in open-access papers (continued):
Sharing a sentence is not in itself a finding about the gene and the disease.
congenital heart disease (3 papers, 2021 to 2024). A heart disease that is present at birth. "The ABL1 gene, which encodes a protein kinase involved in cellular response to stress, differentiation, and adhesion, plays an important role in cardiac development, and a gain-of-function mutation in ABL1 leads to congenital heart defects." (PMID 38886689, 2024). "Recently, germline missense variants in ABL1 have been found to cause an autosomal dominant developmental syndrome with congenital heart disease, skeletal malformations and characteristic facies." (PMID 33223528, 2021).
depression (3 papers, 2016 to 2021). "To probe the potential mechanism of the occurrence of depression, we also detect the expression of ABL1, NF-κB1, STAT3, IL-6, IL-1β, and COX2 in the hippocampus of depressive mice." (PMID 31396300, 2019). "ROS-activated ABL1 mediates the inflammatory signaling pathway, which subsequently leads to the development of GC and GC-related depression." (PMID 31396300, 2019). "Given the role of ROS in depression, GC, and crosstalk with inflammation, we speculated that ROS, ABL1, and inflammation are involved in the development of GC as well as GC-related depression." (PMID 31396300, 2019). "ROS-activated ABL1 mediates inflammation through regulating NF-κB1 and STAT3, which subsequently leads to the development of GC and GC-related depression." (PMID 31396300, 2019). "Interestingly, ROS seems to activate ABL1/NF-κB1-related cytokines (IL-6, IL-1β, and COX2), thus involving itself in the process of depression." (PMID 31396300, 2019). "Taking both clinical and experimental data from in vivo and in vitro studies together, ROS mediate the activation of ABL1 to promote cytokine release by triggering NF-κB and STAT3, which may partially account for the poorer prognosis of GC patients with depression." (PMID 31396300, 2019).
endometrial cancer (3 papers, 2018 to 2022). Primary or metastatic malignant neoplasm involving the endometrium (mucous membrane that lines the endometrial cavity). "Further investigations with different systems biology methods have prioritized ALDH1A1, ABL1 and CCND2 as potential genes involved in endometrial cancer metastasis owing to their high mutation load and expression status." (PMID 36704357, 2022). "ABL1 is targeted by Imatinib Mesylate inhibitor which, in a phase I clinical trial for endometrial cancer, while PDGFRA is targeted by Nintedanib, and Dovitinib inhibitors which are currently under phase II clinical trial and Vatalanib as well as Cediranib, inhibitors under phase I clinical trial." (PMID 36704357, 2022). "The upregulated hsa-mir-200a-b is associated with the decreased expression of the PTCH1, CCND2, PDGFRA, FOSB and ABL1 genes in endometrial cancer tissue while hsa-mir-429 is correlated with the decreased expression of the ALDH1A1 gene, besides some antibodies, PROTACs and inhibitory molecules." (PMID 36704357, 2022). "In conclusion, this study identified key miRNAs (hsa-mir-200a, hsa-mir-429) and target genes ALDH1A1, ABL1 and CCND2 as potential biomarkers for metastatic endometrial cancers from large-scale gene expression data using systems biology approaches." (PMID 36704357, 2022).
erythroleukemia (3 papers, 2022 to 2025). Acute erythroid leukemia characterised by the presence of at least 50% erythroid precursors and at least 20% myeloblasts in the bone marrow. "We next tried to create e13a2 type fusion in a TF-1 cell line, which is a human GM-CSF-dependent erythroleukemia cell line, since transfection of BCR::ABL1 fusion cDNA was reported to induce factor-independent cell growth." (PMID 35999358, 2023).
esophageal cancer (3 papers, 2016 to 2024). A primary or metastatic malignant neoplasm involving the esophagus. "In the other clusters, the genes SCML4, HNRNPF, IFRD1, CSTA, ABL1, etc., have a causal relationship with esophageal cancer." (PMID 38434988, 2024). "Similarly, genes like SCML4, HNRNPF, IFRD1, CSTA, ABL1 in other immune cell clusters also exhibit a causal relationship with esophageal cancer." (PMID 38434988, 2024).
liver cancer (3 papers, 2021 to 2022). An epithelial or non-epithelial malignant neoplasm that arises from the liver. "Multivariate Cox regression analysis further showed that the ABL1 expression level was an independent risk factor for liver cancer prognosis." (PMID 34484330, 2021). "In this study, we used a variety of databases to comprehensively explore the clinical significance of ABL1 in liver cancer, identify possible target pathways, and determine the relationship between ABL1 and immune infiltration." (PMID 34484330, 2021). "Our analysis showed that ABL1 expression was significantly higher in liver cancer tissues than in normal tissues." (PMID 34484330, 2021). "Our results provide a better understanding of the potential value of ABL1 in liver cancer." (PMID 34484330, 2021). "Therefore, we also evaluated the effect of ABL1 expression on immune infiltrating cells in liver cancer using CIBERSORT." (PMID 34484330, 2021). "However, there are few studies on the prognostic value and specific mechanism of ABL1 in liver cancer." (PMID 34484330, 2021).
lymphopenia (3 papers, 2017 to 2021). Reduction in the number of lymphocytes. "The incidences of lymphopenia <1 × 109) in groups 2 and 3 were 58,3% (7/12) and 71.4% (15/21), and VLs in lungs were 18-1952 and 810-2657 SARS-CoV-2 cDNA copies per 100 ABL1, respectively." (PMID 34372615, 2021).
MALT lymphoma (3 papers, 2012 to 2016). An indolent, extranodal type of non-Hodgkin lymphoma composed of small B-lymphocytes (centrocyte-like cells). "Therefore, miR-203 was shown to be a tumor suppressive miRNA targeting ABL1, and miR-203 methylation might be important in pathogenesis of MALT lymphoma." (PMID 23162567, 2012).
metastatic melanoma (3 papers, 2018 to 2020). A melanoma that has spread from its primary site to another anatomic site. "Since resistance is a major impediment to long-term survival for patients with metastatic melanoma, and ABL kinases are activated by ERK pathway components (BRAF, ERK) and activate ERK16, we tested whether ABL1/2 drive BRAFi or BRAFi/MEKi resistance." (PMID 33122628, 2020).
metastatic tumors (3 papers, 2013 to 2018). "In agreement with our above data, the mRNA levels of ABL2 and CTTN, but not of ABL1, were significantly higher in metastatic tumors compared with tumors that did not metastasize." (PMID 29774130, 2018).
myeloid sarcoma (3 papers, 2019 to 2025). A tumor mass composed of myeloblasts or immature myeloid cells. "CP-CML is defined by the presence of the BCR::ABL1 fusion gene, while BP-CML is diagnosed when blasts in peripheral blood (PB) or bone marrow (BM) exceed ≥20%, or when myeloid sarcoma or lymphoblast infiltration is present." (PMID 40507313, 2025).
systemic mastocytosis (3 papers, 2015 to 2025). Systemic mastocytosis (SM) comprises a heterogeneous group of rare acquired and chronic hematological malignancies that are related to an abnormal proliferation of mast cells in tissue, including bone marrow, with or without skin involvement. "Taken together, our results point to SETD2/H3K36me3 deficiency as a mechanism, already identified by our group in systemic mastocytosis, that is reversible, druggable, and BCR::ABL1‐independent, able to cooperate with BCR::ABL1 in driving genetic instability in CML." (PMID 40275711, 2025).
withdrawal syndrome (3 papers, 2024 to 2025). "Other clinical parameters were assessed, including BCR::ABL1 transcript type, withdrawal syndrome (WS), and ELTS score, which are suggested to be important in the TFR trial." (PMID 38667336, 2024). "In this case, the potential for withdrawal syndrome, the importance of regular BCR::ABL1 monitoring, and a quick restart of therapy should levels rise would have been key discussion points, alongside the wish of the patient to prevent ongoing side effects and to stop taking medication every day." (PMID 40161248, 2025). "In the univariate analysis, gender, Sokal score, type of BCR::ABL1 transcript, and withdrawal syndrome did not impact the TFR rate." (PMID 38779092, 2024).
cardiomyopathy (2 papers, 2024 to 2025). A disease of the heart muscle or myocardium proper. "The tyrosine kinase Abl1 is of critical importance in doxorubicin induced cardiomyopathy, and we propose its inhibition as means to diminish risk of cardiotoxicity." (PMID 39285385, 2024). "We propose a strategy to alleviate doxorubicin induced cardiomyopathy by blocking Abl1 activity." (PMID 39285385, 2024). "Additionally, we gained deep insight into the genomic responses of cardiomyocytes as they relate to mitochondrial toxicity, programmed cell death, inflammation and toxic cardiomyopathy that is orchestrated, at least in part, by Abl1 transcriptional cofactor activity." (PMID 39285385, 2024).
childhood cancer (2 papers, 2020 to 2023). "Abnormalities in six genes (NRAS, ABL1, JAK2, KIT, ALK and BRAF) were common in childhood cancers as well as adult cancers, for which at least one approved drug could be a potentially actionable drug." (PMID 33051474, 2020).
cholangiocarcinoma (2 papers, 2023 to 2025). A carcinoma that arises from the intrahepatic biliary tree (intrahepatic cholangiocarcinoma) or from the junction, or adjacent to the junction, of the right and left hepatic ducts (hilar cholangiocarcinoma). "A second tier of high frequency mutations were identified in oncogenes not typically associated with cholangiocarcinoma, including mTOR (17%, 7/42 cases) and ABL1 (14%, 6/42 cases)." (PMID 37095160, 2023).
CNS leukemia (2 papers, 2014 to 2024). "Moreover, 50% of the relapsed children had BCR::ABL1 or TCF3:: PBX1 fusion genes as a high-risk factor for CNS leukemia relapse, consistent with literature reports." (PMID 38519960, 2024).
eosinophilic disorders (2 papers, 2024 to 2025).
exomphalos (2 papers, 2025). "In summary, we identified an extended splice variant in ABL1 leading to haploinsufficiency in a multiplex family with isolated dominant omphalocele." (PMID 40843169, 2025). "Our genetic and experimental findings provide evidence that ABL1 haploinsufficiency is the first monogenic cause for isolated dominant omphalocele." (PMID 40843169, 2025). "Herein, we present genetic and experimental evidence indicating ABL1 haploinsufficiency as the first monogenic cause of isolated dominant omphalocele." (PMID 40843169, 2025). "Identification of ABL1 variants in families with a history of omphalocele could provide valuable insights into the recurrence risk and enable genetic counseling." (PMID 40843169, 2025). "Next, we sought the embryonic expression of ABL1 in the region of the nascent umbilicus, which is the site where an omphalocele is formed." (PMID 40843169, 2025). "Three cases of exomphalos were also found in our cohort in association with imatinib (cases i, v, x), and none were observed with other BCR::ABL1 TKIs or anticancers." (PMID 40442861, 2025).
myocardial infarction (2 papers, 2020 to 2023). Gross necrosis of the myocardium, as a result of interruption of the blood supply to the area, as in coronary thrombosis. "One of the three patients with a BCR::ABL1 mutation had a myocardial infarction prior to the start of TKI." (PMID 37444494, 2023).
Obesity (2 papers, 2022 to 2023). Accumulation of substantial excess body fat. "ABL1 is highly expressed in the subcutaneous fat of obese humans and high-fat diet-induced obese mice, and it is able to regulate diet-induced obesity by improving insulin sensitivity in subcutaneous fat." (PMID 35812879, 2022). "However, our stratified analysis suggested that the adverse effects of obesity on survival were more prominent in patients with certain risk factors, particularly B‐cell immunophenotype and BCR/ABL1 mutation." (PMID 36168702, 2023).
renal carcinoma (2 papers, 2012 to 2019). A carcinoma arising from the epithelium of the renal parenchyma or the renal pelvis. "In renal carcinoma, the levels of ROS are positively correlated with the expression of ABL1." (PMID 31396300, 2019).
renal fibrosis (2 papers, 2022 to 2024). A final common manifestation of a wide variety of chronic kidney diseases characterized by glomerulosclerosis and tubulointerstitial fibrosis. "The nonreceptor tyrosine kinase c-Abl (encoded by the Abl1 gene) has been implicated in the development of renal fibrosis." (PMID 38689280, 2024).
systemic sclerosis (2 papers, 2020 to 2025). A chronic disorder, possibly autoimmune, marked by excessive production of collagen which results in hardening and thickening of body tissues. "Indeed, ABL1 is located downstream of TGF-β, and in preclinical models of systemic sclerosis, a disease which may resemble Scl-cGvHD, the production of proteins of the extra-cellular matrix by TGF-β was significantly decreased in ABL1-deficient cells." (PMID 33162993, 2020).
ameloblastoma (1 paper, 2025). The most common odontogenic tumor, arising from the epithelial component of the embryonic tooth and usually affecting the molar-ramus region of the mandible or maxilla. "Additional studies showed gene expression profile differences between plexiform and follicular ameloblastomas, with follicular ameloblastomas expressing variants of BRAF, KMT2D, and ABL1, while plexiform ameloblastomas expressed variants of ALK, BRAF, KRAS, KMT2D, SMO, KMT2A, and BRCA2." (PMID 38607614, 2025).
anaphylaxis (1 paper, 2020). An acute hypersensitivity reaction that occurs from exposure to an allergen. "Collectively, IL-4 amplifies IgE- and histamine-induced VE dysfunction, fluid extravasation, and the severity of anaphylaxis through a VE-IL-4Rα/ABL1-dependent mechanism." (PMID 32789004, 2020).
aortic root dilatation (1 paper, 2021). "Phenotypes such as skeletal malformations, aortic root dilatation and pneumothorax point towards an overlap with genetic connective tissue disorders and we recommend that ABL1 be borne in mind in such cases." (PMID 33223528, 2021).
bacterial pneumonia (1 paper, 2023). Acute infection of the lung parenchyma caused by bacteria (e.g., Streptococcus pneumoniae, Haemophilus influenzae, Chlamydia pneumoniae, Mycoplasma pneumoniae, and Legionella pneumophila). "Inhibition of ABL1 activity promotes lung regeneration through expansion of an SCGB1A1 + SPC + cell population following bacterial pneumonia." (PMID 37280583, 2023).
bladder transitional cell carcinoma (1 paper, 2012). The most common morphologic subtype of urinary bladder carcinoma (over 90% of cases). "A study of bladder transitional cell carcinoma found a significant reduction in ABL1 expression in cancerous compared with normal tissue." (PMID 22075945, 2012).
cardiac hypertrophy (1 paper, 2025). "Leading kinases included AKT1, MAPK1, MYLK, INSR, and ABL1, all of which are implicated in stress response and cardiac hypertrophy, particularly under physiological conditions." (PMID 40725470, 2025).
chronic GVHD (1 paper, 2023). "Thus, the current BCR::ABL1 level less than 0.06% in patients with chronic GvHD predicts low risk of relapse." (PMID 37798335, 2023). "At the same time, patients without chronic GVHD after allo-HSCT should be classified as high risk with any level of BCR::ABL1." (PMID 37798335, 2023). "BCR::ABL1 level before and after allo-HSCT, prediction moment, and chronic GvHD had the highest value in the model." (PMID 37798335, 2023). "At the same time, if the patient had no chronic GVHD after allo-HSCT till the prediction moment, he should be classified to a high risk group at any BCR::ABL1 level." (PMID 37798335, 2023). "Thus, since day + 100 after allo-HSCT the patients with chronic GvHD and current BCR::ABL1 level equal to or higher than 0.06% can be classified as high risk of relapse." (PMID 37798335, 2023). "According to the map, depending on the presence or absence of chronic GVHD and the definite levels ​​of the BCR::ABL1, the patient can be assigned to a group of high (the relapse risk is over 20%) or low (the relapse risk is less 20%) risk of relapse." (PMID 37798335, 2023).
congenital heart defects and skeletal malformations syndrome (1 paper, 2023). "The biallelic loss of function variant in ABL1 these two siblings share is very different from the gain of function de novo variants identified in ABL1-related congenital heart defects and skeletal malformations syndrome CHDSKM." (PMID 37644014, 2023).
coronary atherosclerosis (1 paper, 2025). Atherosclerosis of the coronary vasculature. "At relapse, one patient had an ABL1 kinase domain (KD) E255V mutation, one had a T3151 mutation (in a patient who was on dasatinib at the time of relapse due to the development of worsening coronary atherosclerosis), and two did not have an ABL1 KD mutation detected." (PMID 40369607, 2025).
Hearing impairment (1 paper, 2021). A decreased magnitude of the sensory perception of sound. "More recently, the clinical spectrum of the ABL1 malformation syndrome has been expanded to include hearing impairment, renal hypoplasia and ocular abnormalities." (PMID 33223528, 2021). "All the affected individuals in this series recapitulate the phenotype of the ABL1 developmental syndrome and additionally we affirm that hearing impairment is a common feature of the condition." (PMID 33223528, 2021).
hydronephrosis (1 paper, 2023). Collection of urine in the renal pelvis that results in dilatation of the renal pelvis and calyces. "For this mouse model, we observed uni- or bilateral hydronephrosis in BCR::ABL1 positive mice driven by urinary obstruction due to myeloid infiltration within the renal pelvis and ureters." (PMID 37161070, 2023). "Strikingly, we observed high MC counts in the BM and kidney as well as hydronephrosis in some recipients, demonstrating the cell-autonomous properties of the BCR::ABL1 positive donor cells." (PMID 37161070, 2023).
hydrops fetalis (1 paper, 2025). Hydrops fetalis is a severe and challenging fetal condition usually defined as the excessive accumulation of fetal fluid within the fetal extravascular compartments and body cavities that manifests as edema, pleural and pericardial effusion and ascites. "The findings of our disproportionality analysis study present substantial evidence that BCR::ABL1 TKI exposure is associated with the occurrence of pregnancy complications such as hydrops fetalis, polyhydramnios among fetuses or newborns, which were more specific to dasatinib." (PMID 40442861, 2025). "Within the whole cohort, 5 reports included a mention of hydrops fetalis and BCR::ABL1 TKI exposure: one was associated with imatinib, three with dasatinib, and one with nilotinib." (PMID 40442861, 2025).
hyperuricemia (1 paper, 2025). An abnormally high level of uric acid. "For example, in hyperuricemia, we identified ADR-DP proteins that included PDGFRA, FLT3, and ABL1 as having high values in the z axis." (PMID 39954672, 2025).